BDNF (brain derived neurotrophic factor)
Diseases named in the same sentence as BDNF in open-access papers (continued):
Sharing a sentence is not in itself a finding about the gene and the disease.
Cognitive impairment (continued). "Finally, a synergistic treatment with UA (500 mg) and resistance/endurance training significantly increased T3DM biomarkers, such as brain-derived neurotrophic factor (BDNF) and IGF-1, by reversing the cognitive disorder caused by diabetes in the hippocampus of diabetic aged rats." (PMID 41516048, 2025). "Therefore, in the United States, a phase 1 clinical trial (NCT05040217) is currently underway, investigating the administration of brain-derived neurotrophic factor (BDNF) into the brain using AAV2-BDNF vectors in patients with early AD or mild cognitive impairment (MCI)." (PMID 39596378, 2024). "Luteolin could also ameliorate cognitive deficits by regulating the cholinergic system activity, inhibiting oxidative stress, and increasing the level of brain-derived neurotrophic factor (BDNF) and tyrosine kinase receptor (TrkB) expression in the cerebral cortex." (PMID 38904713, 2024). "Additionally, in PAH reactions, reduced BDNF expression could lead to abnormal synaptic function related to brain cognition, resulting in cognitive impairment." (PMID 39020327, 2024). "Moreover, the reduction of serum BDNF may be a vital neuropathophysiological mechanism of cognitive impairment in T2DM patients." (PMID 38648255, 2024). "In addition to the slightly higher mean sMMSE score, the considerably higher BDNF levels of the patients on DPP-4 inhibitor treatment suggest that the DPP-4 inhibitors may have protective effects against cognitive impairment." (PMID 38510866, 2024). "Therefore, upregulating NF-κB activation-suppressed BDNF expression may be useful for the improvement of cognitive impairment." (PMID 39203872, 2024). "In another cognitive impairment model, the streptozotocin-induced rodent model, treatment with M. officinalis reversed the learning and memory deficits observed in the Y-maze and passive avoidance task, accompanied by increased expression of BDNF and NOS in the hippocampus." (PMID 39457003, 2024). "However, when we injected SIRT1 overexpressed virus into the VGULT1 mice’s CA1 region, the expression of SIRT1 and BDNF was significantly increased, synaptic plasticity impairment and neuronal excitability were also recovered, and the cognitive impairment induced by anesthesia/surgery was improved." (PMID 38783169, 2024). "In addition, the fact that the STZ group’s cognitive impairment improved after T3 supplementation could mean that BDNF had a neurotrophic effect in the hippocampus." (PMID 39513900, 2024). "Of note, increasing evidence suggested that upregulating the expression of the ERK(1/2)/cyclic AMP response element-binding protein (CREB)/brain-derived neurotrophic factor (BDNF) pathway-related proteins may ameliorate neuronal damage, thereby alleviating induced cognitive impairments." (PMID 39203778, 2024). "Furthermore, many animal studies have shown that IF reduces cognitive deficits by stimulating a reduction in BDNF production in the hippocampus, cerebral cortex, and striatum by suppressing the expression of proinflammatory cytokines, such as IL-1β, and enhancing neurotrophic support." (PMID 38276070, 2024). "However, over time, BDNF may decline to a level that signals more severe neurological dysfunction and cognitive impairment." (PMID 38534322, 2024). "Likewise, BDNF levels decrease considerably in ageing, contributing to cognitive deficits." (PMID 38987448, 2024). "GPR17 may contribute to neuronal damage and cognitive impairments by regulating the NF-κB p65/CREB/BDNF(cAMP response element-binding protein/brain-derived neurotrophic factor) signaling pathway, thus promoting the expression of oxidative stress and inflammatory factors." (PMID 39355779, 2024). "People who have been physically active or participated in regular exercise programs before becoming elderly delay cognitive decline, have lower Aβ expression, are at less risk of cognitive impairment when elderly, and have increased BDNF compared to those who have not." (PMID 38337492, 2024).
Cognitive impairment (continued). "Furthermore, some studies suggest that decreased brain-derived neurotrophic factor (BDNF) might explain the cognitive impairment in burnout." (PMID 37850039, 2023). "Therefore, we proposed the NfL/BDNF ratio as a new index for cognitive impairment that could have clinical significance in SUD patients." (PMID 36674698, 2023). "Chronic stressors lead to decreased brain-derived neurotrophic factor (BDNF) expression, resulting in a decreased number of neuronal synapses in the medial prefrontal cortex and hippocampus and finally affecting the function of cognitive-related brain areas, showing cognitive impairment." (PMID 37123418, 2023). "Although BDNF does not have a causative role in the pathology, it may serve as a useful biomarker for monitoring cognitive impairment due to diabetes." (PMID 36936159, 2023). "Plasma BDNF may serve as a predictive biomarker of cancer-related cognitive impairment." (PMID 37770565, 2023). "Studies with ApoE4 and BDNF-Met allele carriers have demonstrated a correlation between genotype and memory impairment in older non-symptomatic ApoE4 carriers, in patients with mild cognitive impairment, and in preclinical AD." (PMID 37446337, 2023). "However, two previous studies have examined the influence of the BDNF Val66Met genotype in PTSD vs TE groups on general cognition and found cognitive deficits in participants with the BDNF Met allele in the PTSD, but not the TE groups." (PMID 36977737, 2023). "However, considering that BDNF expression is highly altered in structures essential for memory processes, such as HIPP and para-hippocampal areas, our study focused on BDNF changes in substance use disorders associated with cognitive impairment." (PMID 37509436, 2023). "Therefore, research on BDNF as a biomarker of cognition in schizophrenia needs to be tailored to specific subgroups of patients, including stratification according to different degrees of a patient ́s cognitive impairment." (PMID 37445746, 2023). "According to our results, chronic post-stroke treatment with Q10 (200 mg/kg) could significantly reduce brain edema and attenuate cognitive impairments, while decreasing depressive and anxiety-like behavior and increasing BDNF levels as well as SOD activity after global cerebral I/R injury in rats." (PMID 35656440, 2022). "The changes in BDNF, GDNF and IGF-II in both groups may be related to several variables including the intensity and duration of the intervention, timing of measurement, genetic polymorphism and cognitive impairment, which may be clarified in future studies." (PMID 36556107, 2022). "Hence, the epigenetic improvement of BDNF-TrkB signaling may be a promising target for withdrawing isoflurane-induced cognitive impairments." (PMID 36230916, 2022). "Finally, current data indicate that exposure to high concentrations of sevoflurane in aged mice may cause cognitive impairment and AHN inhibition, which may be related to the BDNF/TrkB and NT-3/TrkC pathways." (PMID 35309893, 2022). "However, recent studies have shown that low serum BDNF levels are associated with cognitive impairment in patients with first-episode and chronic SCZ and non-medicated patients with current depressive episodes of BD II and MDD." (PMID 36406755, 2022). "Therefore, exercise intensity, exercise duration and presence of cognitive impairment may be essential factors for exercise-induced changes in serum BDNF levels." (PMID 36556107, 2022). "Experimental data suggest the relevance of the muscle-brain axis and the relationship between muscle contraction and release of brain-derived neurotrophic factor, however, the impact of this relationship on cognition remains unclear, especially in people with diagnosis of cognitive impairment." (PMID 35879665, 2022). "However, studies in rodents reported that Zn supplementation could increase the expression of BDNF in the hippocampus and prevent cognitive impairment." (PMID 36235574, 2022).
Cognitive impairment (continued). "Therefore, BDNF is an important mediator between cognitive impairment and neuroinflammation." (PMID 35235140, 2022). "Val66Met MS patients had a higher volume of hippocampal subfields than BDNF Val66Val MS patients, suggesting that BNDF Val66Met polymorphism may protect MS patients from cognitive impairment and hippocampal atrophy, and that the BDNF genotype may be a biomarker for predicting cognitive prognosis." (PMID 35743271, 2022). "The amount of 27-kDa BDNF is increased in the CSF samples of PD patients compared with normal controls, whereas serum BDNF levels are significantly lower in PD patients than in healthy controls, which are correlated with motor impairment and cognitive deficits in PD." (PMID 35996194, 2022). "It was found that the CREB/BDNF pathway was downregulated in Alzheimer's disease and vascular dementia, indicating that the expression of CREB/BDNF in the hippocampus may be associated with cognitive impairments." (PMID 36478990, 2022). "Hence, Q10 may mitigate the cognitive impairments of global cerebral I/R via different neuroprotective mechanisms such as decreasing inflammation and oxidative stress as well as increasing BDNF." (PMID 35656440, 2022). "Also, BDNF and TrkB could be used as noninvasive and objective candidate markers and predictive indices of cognitive impairment in children with SDB." (PMID 36683819, 2022). "In addition, continuous treatment of TQ (20 mg/kg/day, intraperitoneally, for 42 days) ameliorated D-Gal/AlCl3-induced cognitive deficit by protecting against oxidative stress, enhancing cholinergic function and increasing brain-derived neurotrophic factor (BDNF) and Bcl-2 levels." (PMID 34073784, 2021). "Third, due to the cross-sectional design, this study could not reveal the causal relationship between decreased BDNF and cognitive impairment in geriatric schizophrenia patients." (PMID 34239458, 2021). "Additionally, we posit that VAD may reduce the expression of GABA receptors and downregulate BDNF in the brain by disturbing intestinal microbiota (especially Lactobacillus), thus leading to histological and cognitive impairment in AD." (PMID 34790112, 2021). "The role of BDNF in cognitive deficits at different stage of illness remains unclear." (PMID 34625629, 2021). "Therefore, BDNF may be an important mediator of the aggravated cognitive deficits after long-term VAD." (PMID 34790112, 2021). "The associations of cytokines and BDNF during chemotherapy may not be indicative in patients who developed cognitive impairment months after the completion of chemotherapy." (PMID 33985854, 2021). "Based on experimental evidence, low levels of neuroactive peptides, such as VGF and BDNF, may contribute to memory and cognitive impairments, whereas decreased levels of CysC and the prohormone convertase-binding proteins 7B2 and proSAAS could promote amyloidogenesis." (PMID 34565482, 2021). "This study aimed to examine whether peripheral BDNF levels were associated with cognitive deficits in LLS, which has not been explored yet." (PMID 34239458, 2021). "Importantly, the equilibrium of Th1 and Th2 cytokines may be disrupted, which can lead to BDNF dysregulation and cognitive impairment." (PMID 33985854, 2021). "Indeed, HF diets can hypermethylate the BDNF gene and result in cognitive impairment." (PMID 34836233, 2021). "Moreover, decreased BDNF is related to attention deficits, indicating that BDNF might be a candidate biomarker of cognitive impairments in LLS patients." (PMID 34239458, 2021). "Additionally, increasing BDNF levels could mimic beneficial effects of exercise, including improving cognitive impairment and promoting combined adult hippocampal neurogenesis in 5×FAD mice." (PMID 34071457, 2021).
Cognitive impairment (continued). "Many studies have shown that activation of BDNF signaling pathway could attenuate cognitive impairment after surgery and reduce the elevated levels of inflammatory cytokines (Chen, Wu, & Gu, 2018; Wei, Zheng, & Liu, 2018), suggesting the critical role of BDNF in the development of POCD." (PMID 33405375, 2020). "Thus, although the relationship between serum BDNF and AD symptomology may be unclear, current research suggests that inheritance of BDNF Met leads to more severe or more rapidly progressing cognitive deficits in the presence of AD pathology, in most cases." (PMID 32218234, 2020). "PD is a disabling neurodegenerative disease that may be associated with nonmotor symptoms, such as cognitive deficits, and is often accompanied by altered BDNF production." (PMID 33029119, 2020). "As such, the study has established that post-exercise increases in plasma BDNF are related to subsequent learning in older adults, with important implications for the design of future multidomain intervention studies that aim to combat the challenge of late-life cognitive impairment." (PMID 32157099, 2020). "However, whether patients affected by OSAS have altered BDNF levels and whether such alteration may be reflective of their cognitive impairment is still controversial." (PMID 31951637, 2020). "Hence, it is possible that smoking-induced cognitive deficits (maybe through free radical mechanisms) lead to an increase in BDNF levels in order to reverse smoking’s harmful effects, and prevent further damage." (PMID 30659208, 2019). "Moreover, comparatively high BDNF being associated with more cognitive impairment in smokers needs to be viewed in the context of no overall differences in BDNF in these smokers compared to nonsmokers." (PMID 30659208, 2019). "Taken together, this screening assay can identify inducers of Bdnf expression in neurons, and may be useful for mining candidates for therapeutic agents of dementia and other BDNF-related neurological diseases as well as inhibitors of aging-related cognitive impairment." (PMID 31413298, 2019). "In 2015, Xiang and coworkers reported an impaired cognition as well as the downregulation of Akt, CREB and BDNF in the hippocampi of streptozotocin-treated rats, results that may offer a new way to impede diabetes-induced encephalopathy and cognitive deficits in AD." (PMID 31137621, 2019). "Although SIE may lead to progressive fatigue, causing excessive activation of the central nervous system and subsequent cognitive impairments, it might also induce the production of neurotrophins such as BDNF or IGF-1, positively affecting neurogenesis and synaptic plasticity in the brain." (PMID 32038149, 2019). "Increased serum BDNF levels after administering DW2009 may provide preliminary insight into the underlying effects of cognitive improvement, which suggests the importance of the gut-brain axis in ameliorating cognitive deficits in MCI." (PMID 30717153, 2019). "Because BDNF is associated with cognitive flexibility, treatment with this trophic factor or other pharmacological agents that stimulate an increase in BDNF expression may be an effective therapy in alleviating slowing cognitive flexibility in other models of cognitive impairment." (PMID 31191635, 2019). "Because BDNF is an important mediator for neuronal survival and synaptic plasticity to maintain brain functions, possible contribution of BDNF/TrkB dysfunction in the cognitive deficits in PD patients was hypothesized." (PMID 30463271, 2018). "However, viral knockdown of neuronal BDNF in the hippocampus of APP/PS1 mice (in the absence of BFCN loss) neither increased the level of Aβ nor caused cognitive deficits." (PMID 29520217, 2018).
Cognitive impairment (continued). "In summary, this study has provided new evidence to support decreased BDNF serum level in T2DM patients, which was significantly associated with the degree of cognitive impairments in T2DM, suggesting that circulating BDNF level may be considered as biomarker of cognitive function in T2DM patients." (PMID 29423073, 2018). "Thus, it is likely that decreased BDNF expression in the hippocampus of Hx rats may be responsible for the impaired LTP in relation with cognitive impairments." (PMID 28767193, 2017). "Our findings suggest that after ischemic stroke, treatment with rTMS promoted the functional recovery of cognitive impairments by inhibiting apoptosis and enhancing neurogenesis in the hippocampus and that this mechanism might be mediated by the BDNF signaling pathway." (PMID 28824455, 2017). "Electro-acupuncture at DU20 could markedly ameliorate cognitive impairments, reduce aberrant overexpression of β-amyloid, and inhibit neuronal apoptosis, significantly enhance expression levels of mature brain-derived neurotrophic factor (BDNF) and pro-BDNF in APP/PS1 mice." (PMID 29284465, 2017). "Indeed, a decreased level of pro-BDNF was shown in mild cognitive impairment (MCI) patients." (PMID 28852418, 2017). "Interestingly, genetic risk score based on the accumulation of multiple risk alleles in BDNF, COMT and APOE for AD combining multiple genetic influences may be more useful in predicting late-life cognitive impairment than individual polymorphisms." (PMID 28443016, 2017). "Preliminary evidence suggests that changes in plasma brain-derived neurotrophic factor (BDNF) levels may contribute to the occurrence of chemotherapy-associated cognitive impairment (CACI), and a previous study suggested that carriers of the BDNF Met homozygous genotype are protected from CACI." (PMID 29258453, 2017). "Thus, we propose that the suppression of hippocampal GSK-3β phosphorylation induced by the SM70EE-enhanced BDNF/PI3K/Akt signaling pathway contributes to the inhibition of APP processing by downregulating BACE1 to ameliorate the cognitive disorders induced by an I.C.V. injection of Aβ1–42." (PMID 29137190, 2017). "Thus, not only is reduced serum BDNF level an early marker of cognitive impairment of neurodegenerative etiology, but it also reflects pathogenetic aspects of neurocognitive disorders, such as the reduced support of synaptic plasticity underlying in memory process." (PMID 27597800, 2016). "We should also consider the possibility that the cases from the old cohort might include mild cognitive impairment or even dementia and, therefore, that their BDNF levels became lower, while we excluded persons with a low Mini-Mental State of Examination score from the analyses." (PMID 27070410, 2016). "Thus, inflammation-induced BDNF could be a mediator of cognitive impairment and chronic pain in GWI." (PMID 27352030, 2016). "The aging-induced cognitive deficits depends on the intensity level of TMS, which are closely associated with hippocampal structural synaptic plasticity that plays an important role in regulating cognitive behavior via changing structural synaptic plasticity through BDNF signaling." (PMID 27445961, 2016). "The fact that PD patients may also display cognitive deficits and that these functions may be dependent on BDNF activity suggest that a cognitive rehabilitation protocol aimed at improving these specific cognitive functions may also involve modification of this neurotrophin." (PMID 25852518, 2015). "Thus, in this pilot study we evaluated the effect of a cognitive rehabilitation protocol focused on the training of executive functioning and measured BDNF serum levels in a group of PD patients with mild cognitive impairment, as compared to the effect of a placebo treatment (n = 7/8 group)." (PMID 25852518, 2015).